RNU6-58P (RNA, U6 small nuclear 58, pseudogene)
Synonyms: formerly RNU6-58
Gene: Small nuclear RNA gene on chromosome 13 (23,217,432 to 23,217,534, reverse strand). Ensembl gene ENSG00000252952.
Homologues: Orthologues: chimpanzee U6 (99% identical), rat LOC120095365 (68% identical), mouse Gm24211 (66% identical). Paralogues in human: RNU6-132P (76% identical), RNU6-1314P (74% identical), RNU6-345P (74% identical), RNU6-536P (74% identical), RNU6-558P (74% identical), RNU6-873P (74% identical), RNU6-1060P (73% identical), RNU6-1266P (73% identical), RNU6-483P (73% identical), RNU6-656P (73% identical), RNU6-738P (73% identical), RNU6-1011P (72% identical), and 1284 more.